FAM8A1 (family with sequence similarity 8 member A1)
Description:
Plays a role in the assembly of the HRD1 complex, a complex involved in the ubiquitin-proteasome-dependent process of ER-associated degradation (ERAD).
Synonyms: AHCP
Tractability: Antibody: UniProt predicts a signal peptide or a membrane-spanning region. PROTAC: its protein half-life has been measured.
Gene: Protein-coding gene on chromosome 6 (17,600,302 to 17,611,719, forward strand). Ensembl gene ENSG00000137414.
Subcellular location: Membrane
Subcellular location (Human Protein Atlas): Golgi apparatus
Gene Ontology:
Molecular function: protein binding
Biological process: ERAD pathway
Cellular component: Hrd1p ubiquitin ligase complex; membrane
Genetic constraint (gnomAD): Loss-of-function variants: 18 observed, 21.5 expected, observed/expected ratio (o/e) 0.84, 90% interval 0.58 to 1.24. The synonymous counts are far from expectation, so gnomAD's model fits this gene poorly and the ratio says little. Missense variants: 534 observed, 434.24 expected, observed/expected ratio (o/e) 1.23, 90% interval 1.14 to 1.32. Synonymous variants: 242 observed, 189.12 expected, observed/expected ratio (o/e) 1.28, 90% interval 1.15 to 1.42.
Homologues: Orthologues: chimpanzee FAM8A1 (99% identical), macaque FAM8A1 (96% identical), rabbit FAM8A1 (87% identical), pig FAM8A1 (81% identical), dog FAM8A1 (78% identical), mouse Fam8a1 (76% identical), rat Fam8a1 (76% identical), guinea pig FAM8A1 (76% identical), zebrafish fam8a1b (41% identical), zebrafish fam8a1a (36% identical), tropical clawed frog fam8a1 (34% identical), Drosophila melanogaster CG8237 (20% identical), and 1 more.
Diseases named in the same sentence as FAM8A1 in open-access papers:
FAM8A1 is named in the same sentence as 4 diseases in open-access papers, as found by Europe PMC text mining. Sharing a sentence is not in itself a finding about the gene and the disease. The quoted sentences say what the papers report.
Alzheimer disease (1 paper, 2020). A progressive, neurodegenerative disease characterized by loss of function and death of nerve cells in several areas of the brain leading to loss of cognitive function such as memory and language. "The DMP that was most significantly associated with AD relative to CN was annotated to FAM8A1, which encodes a protein that is associated with endoplasmic reticulum-associated degradation of proteins with roles in Alzheimer’s disease pathogenesis." (PMID 32539856, 2020).
astrocytomas (1 paper, 2021). "Interestingly, the top-ranked gene (FAM8A1) was identical to the top-ranked gene for Family 1; however, as with low-grade astrocytomas, this gene has not been associated directly with Wilms tumors." (PMID 34624066, 2021).
Wilms tumor (1 paper, 2021). An embryonal neoplasm characterized by the presence of epithelial, mesenchymal, and blastema components. "For Family 2 (Wilms tumor), the top-five ranked genes were FAM8A1, TRPM3, PAH, PCK1, and PCK2." (PMID 34624066, 2021).
FAM8A1 also shares sentences with these, for which no sentence is quoted: schizophrenia (1 paper).